PGK1 (phosphoglycerate kinase 1)
Description:
Catalyzes one of the two ATP producing reactions in the glycolytic pathway via the reversible conversion of 1,3-diphosphoglycerate to 3-phosphoglycerate. Both L- and D-forms of purine and pyrimidine nucleotides can be used as substrates, but the activity is much lower on pyrimidines. In addition to its role as a glycolytic enzyme, it seems that PGK1 acts as a polymerase alpha cofactor protein (primer recognition protein). Acts as a protein kinase when localized to the mitochondrion where it phosphorylates pyruvate dehydrogenase kinase PDK1 to inhibit pyruvate dehydrogenase complex activity and suppress the formation of acetyl-coenzyme A from pyruvate, and consequently inhibit oxidative phosphorylation and promote glycolysis. May play a role in sperm motility.
Synonyms: PGKA; MIG10; HEL-S-68p
Tractability: Small molecule: a structure with a bound ligand is known; a high-quality ligand is known; it has a high-quality binding pocket. PROTAC: ubiquitination databases record sites on it; its protein half-life has been measured; a small molecule that binds it is known.
Target class: Enzyme; Transferase
Chemical probes: TERAZOSIN
Safety:
Unwanted effects reported when the protein is acted on. In parentheses: how it was acted on, where the effect was seen, and who reports it.
drug toxicity (source: ClinPGx)
Gene: Protein-coding gene on chromosome X (77,910,739 to 78,129,295, forward strand). Ensembl gene ENSG00000102144.
Subcellular location: Cytoplasm, cytosol; Mitochondrion matrix
Subcellular location (Human Protein Atlas): End piece; Mid piece; Principal piece
Pathways (Reactome):
Metabolism: Gluconeogenesis; Glycolysis
Disease: Manipulation of host energy metabolism
Signal Transduction: MTOR signalling
Gene Ontology:
Molecular function: phosphoglycerate kinase activity; protein binding; protein serine kinase activity; protein serine/threonine kinase activity; protein-disulfide reductase [NAD(P)H] activity; ADP binding; ATP binding; transmembrane transporter binding
Biological process: cellular response to hypoxia; epithelial cell differentiation; glycolytic process; negative regulation of angiogenesis; negative regulation of pyruvate decarboxylation to acetyl-CoA; plasminogen activation; canonical glycolysis; gluconeogenesis
Cellular component: cytosol; extracellular exosome; extracellular region; membrane; membrane raft; mitochondrial matrix
Homologues: Orthologues: macaque PGK1 (99% identical), mouse Pgk1 (98% identical), guinea pig PGK1 (97% identical), rat Pgk1 (97% identical), pig PGK1 (97% identical), dog PGK1 (96% identical), zebrafish pgk1 (89% identical), tropical clawed frog pgk1 (86% identical), Caenorhabditis elegans pgk-1 (72% identical), Drosophila melanogaster Pgk (70% identical), Drosophila melanogaster CG9961 (60% identical). Paralogues in human: PGK2 (87% identical).
Diseases named in the same sentence as PGK1 in open-access papers:
PGK1 is named in the same sentence as 210 diseases in open-access papers, as found by Europe PMC text mining. Sharing a sentence is not in itself a finding about the gene and the disease. The quoted sentences say what the papers report.
breast carcinoma (83 papers, 2002 to 2025). "While PGK1 mRNA is identified in EVs associated with breast cancer, it is overexpressed in breast cancer." (PMID 40214422, 2025). "NEAT1_1 accelerates glycolytic activity in breast cancer through substrate channeling of PGK1, PGAM1, and ENO1, bringing them into close association in the cytoplasm." (PMID 40804479, 2025). "Studies have demonstrated that the level of PGK1 K131cr in advanced breast cancer cells is significantly lower than that in early-stage cells, suggesting that reduced levels of PGK1 K131cr are associated with a poorer prognosis in breast cancer patients." (PMID 41000388, 2025). "Recent research has demonstrated that PGK1 expression levels are frequently elevated in breast cancer and are closely associated with the invasive and metastatic capabilities of cancer cells." (PMID 39590319, 2024). "A multitude of studies have corroborated the association between PGK1 overexpression and the pathogenesis and progression of breast cancer, highlighting its role in facilitating tumor growth and metastasis." (PMID 39590319, 2024). "Various literature confirms that phosphorylation of PGK1 at S203 is associated with the occurrence and development of tumors and poor prognosis, including breast cancer and glioma." (PMID 36358653, 2022). "Collectively, these results suggested that PGK1 expression has a closely correlation with gene mutations in breast cancer." (PMID 34291087, 2021). "More notably, via the pan‐cancer analysis in our study, the mRNA expression level of PGK1 was significantly associated with the prognosis of multiple cancers, including head and neck, liver, and breast cancer." (PMID 34668665, 2021). "Through six algorithms including MCP-counter, quanTIseq, CIBERSORT, xCell, and TIMER, we estimated the associations of PGK1 with the infiltration levels of lymphocytes across breast cancer." (PMID 34790279, 2021). "Researchers have found that enhanced glycolysis activity combined with higher PGK1 expression in breast cancer was associated with pro‐tumor immunity via upregulation of immune/inflammation pathways, especially the IL‐17 signaling pathway." (PMID 34668665, 2021). "The results indicated that PGK1 overexpression was an independent risk factor for overall death in breast cancer." (PMID 32070368, 2020). "High expression of MZF1, HK2, or PGK1 was also associated with poor survival of patients with breast cancer, endometrial carcinoma, glioma, head and neck carcinoma, lung cancer, lymphoma, pancreatic cancer, or renal clear cell carcinoma." (PMID 32042322, 2020). "We found that the PGK1 expression is associated with the metastasis status and the poor prognosis of patients with breast cancer." (PMID 32276500, 2020). "An analysis of publicly available datasets further suggested that PGK1 expression is associated with metastasis status and poor prognosis in patients with breast cancer." (PMID 32276500, 2020). "We found that PGK1 mRNA level was significantly associated with progressive pathologic TNM stage in breast carcinoma (BRCA), CESC, liver hepatocellular carcinoma (LIHC), and lung adenocarcinoma (LUAD)." (PMID 31578148, 2019). "For example, high levels of phosphoglycerate kinase-1 (PGK1) expression have been associated with shorter survival in breast cancer patients treated with paclitaxel chemotherapy." (PMID 31682620, 2019). "In breast carcinoma, elevated PGK1 mRNA level and promoter hypomethylation were associated with poor prognosis." (PMID 31578148, 2019). "Most of these PGK1 variants, M189I, A199V, V216F and F241S, are reported to be found in breast carcinoma; the other variants, R38M, R65W and G166D are reported to be present in lung, liver and endometrium carcinoma." (PMID 29995887, 2018).
breast carcinoma (continued). "PGK1 over-expression has been shown to associate with the poor prognosis in breast cancer, liver cancer, lung cancer, gallbladder cancer and prostate cancer." (PMID 28903403, 2017). "Furthermore, PGK1 has a potential utility as a diagnostic biomarker for breast cancer and is anticipated to serve as a critical indicator for early screening and prognostic evaluation." (PMID 39590319, 2024). "Notably, phosphoglycerate kinase 1 (PGK1) is intimately associated with the regulation of hypoxia-inducible factors in breast cancer and plays a crucial role in modulating glycolytic processes." (PMID 39590319, 2024). "Furthermore, research into the mechanisms underlying breast cancer has identified PGK1 as a crucial component in various signaling pathways." (PMID 39590319, 2024). "Similarly, in breast cancer patients, upregulation of PGK1 at both transcriptional and protein levels was associated with poor survival and prognosis." (PMID 39712033, 2024). "The oncogenic role of PGK1 is closely associated with promoting cell proliferation and inhibiting apoptosis in a variety of cancers, including liver cancer colon cancer, breast cancer and GBM." (PMID 37723547, 2023). "Furthermore, a higher expression of PGK1 was associated with poor prognosis in breast cancer, as it stimulated breast cancer progression and metastases." (PMID 35622738, 2022). "Furthermore, the expression of PGK1 is significantly associated with poor prognosis and resistance to paclitaxel chemotherapy in breast cancer." (PMID 33584825, 2021). "In order to identify the correlation of mutations which could guide the therapy of breast cancer and PGK1 expression, the Mann-Whitney U analysis was performed to identify crucial gene mutations correlated with PGK1 expression." (PMID 34291087, 2021). "In addition to lung cancer or brain tumors from previous studies, we observed that PGK1 was significantly associated with overall and disease-free survival in breast cancer patients." (PMID 34091600, 2021). "Thus, the PGK1 signature was an independent and the most important risk factor of the prognosis of breast cancer." (PMID 34291087, 2021). "PGK1 has been recorded to have oncogenic roles and is associated with a poor prognosis in several cancers, such as prostate cancer, pancreatic cancer, gastric cancer, liver cancer and breast cancer." (PMID 33747900, 2021). "Therefore, future experimental verification of the mechanism underlying PGK1 regulation of tumor metastasis and its multi-gene prognostic value for breast cancer patients is warranted." (PMID 34291087, 2021). "Moreover, miR-16-1-3p expression negatively correlated with breast cancer lung metatstasis, and PGK1 expression positively associated with breast cancer lung metatstasis." (PMID 33344462, 2020). "In addition, correlational studies involving patients with breast cancer revealed an association of PGK1 with paclitaxel resistance and cell survival factors, such as HIF-1α and immune checkpoints, although these need to be further investigated in future studies." (PMID 40214422, 2025). "However, the expression patterns of PGK1 in various types of breast cancer and the unique roles of PGK1 as a diagnostic marker of poor prognosis in breast cancer remain unknown." (PMID 34291087, 2021). "Taken together, PGK1 may act as a reliable risk factor of breast cancer prognosis." (PMID 34790279, 2021). "However, the precise roles and the underlying mechanism of PGK1 in affecting paclitaxel treatment in breast cancer remain unknown, and further exploration is required." (PMID 33747900, 2021). "Herein, we evaluated the significant associations between PGK1 and clinical phenotypes (pathological T stage (T1-4), pathological N stage (N0-3), pathological M stage (M0 and M1), and survival status (alive and dead)) of breast cancer patients in TCGA dataset, as shown in Sankey diagram." (PMID 34790279, 2021).
breast carcinoma (continued). "There is limited information on the relevance of PGK1 to breast cancer cell survival and progression." (PMID 40214422, 2025). "Similar to NEAT1 in breast cancer, the c-Myc-responsive lncRNA glycoLINC (gLINC) promotes glycolysis by acting as a scaffold for glycolytic enzymes, including PGK1, ENO1, PKM2, and LDHA, with indirect binding to PGAM1." (PMID 40804479, 2025). "PGK1 is an effective therapeutic target in the diagnosis, prognosis, and treatment of cancers, including breast cancer." (PMID 39770478, 2024). "In the treatment of liver cancer, breast cancer, colorectal cancer, and prostate cancer, PGK1 is considered a critical target." (PMID 38256104, 2024). "Studies have found that compared with early breast cancer cells, the level of PGK1 K131cr in advanced breast cancer cells is lower, which indicates that low levels of PGK1 K131cr are associated with poor prognosis in breast cancer patients." (PMID 39513918, 2024). "Under hypoxic conditions, decreased recruitment of FOXO3a in the LINC00926 promoter region inhibits the transcription of LINC00926, thereby increasing the expression of phosphoglycerate kinase 1 (PGK1) to promote Warburg effect in breast cancer cells." (PMID 38505423, 2024). "PGK1 has been identified as an independent prognostic marker for chemoresistance to paclitaxel treatment in patients with breast cancer, and patients with elevated PGK1 levels who are receiving paclitaxel chemotherapy have significantly shorter survival." (PMID 39590296, 2024). "Research indicates that downregulation of PGK1 expression can inhibit proliferation, migration, and invasion of breast cancer cells, as well as reverse epithelial–mesenchymal transition (EMT)." (PMID 39590319, 2024). "Currently, additional investigations are imperative to elucidate the precise mechanisms by which PGK1 influences the onset and progression of breast cancer." (PMID 39590319, 2024). "Subsequent investigations into PGK1 revealed that the viability of breast cancer cell lines with downregulated PGK1 expression was markedly diminished following Paclitaxel treatment." (PMID 39590319, 2024). "This review consolidates current research on the regulation of glucose metabolism and the function of PGK1 in breast cancer within hypoxic conditions." (PMID 39590319, 2024). "Despite advancements in the investigation of PGK1 in breast cancer, numerous critical issues remain to be addressed." (PMID 39590319, 2024). "It is anticipated that future research will further delineate the role of PGK1 in breast cancer, thereby providing a more comprehensive theoretical basis for its treatment and prevention." (PMID 39590319, 2024). "Currently, the potential impact of alterations in BHLHE41 expression levels on PGK1 expression and subsequent breast cancer progression remains an area that necessitates further investigation and validation." (PMID 39590319, 2024). "A substantial upregulation of PGK1 expression has been observed across various breast cancer subtypes, with the expression levels of PGK1 demonstrating a strong correlation with tumor malignancy and prognosis." (PMID 39590319, 2024). "These include elucidating the upstream regulatory mechanisms governing PGK1 in the pathogenesis and progression of breast cancer, as well as understanding the interactions between PGK1 and other signaling pathways." (PMID 39590319, 2024). "In this study, a novel prognostic model was developed to optimize treatment, improve clinical prognosis, and screen potential phosphoglycerate kinase 1 (PGK1) inhibitors for breast cancer treatment." (PMID 39770478, 2024). "Previous research has shown that the E3 ligase STUB1 promotes the ubiquitination of the rate-limiting enzyme PGK1, thereby inhibiting the Warburg effect, tumor growth, and metastasis in breast cancer." (PMID 38993561, 2024). "The research advancements concerning PGK1 in breast cancer offer significant insights into the pathogenesis and therapeutic strategies for this malignancy." (PMID 39590319, 2024).
breast carcinoma (continued). "PGK1 down-regulation inhibits cell proliferation, invasion, and metastasis in breast cancer in vitro and in vivo." (PMID 39770478, 2024). "In line with this, a novel breast cancer signature consisting of CRGs such as PGK1, SLC52A2, and RAD23B has shown potential for prognosis prediction, with RAD23B emerging as a promising target linked to disease progression and drug resistance." (PMID 39867656, 2024). "Specifically, in breast cancer, miR-16 inhibits PGK1 expression and consequently inhibits aerobic glycolysis, a hallmark of cancer, decreasing glucose uptake as well as lactate and ATP production." (PMID 38813102, 2024). "As research on PGK1 advances, it is anticipated that our comprehension of breast cancer pathogenesis will be enhanced, thereby facilitating the development of more efficacious treatment modalities for patients." (PMID 39590319, 2024). "FOXO3A induces LINC00926 to limit breast cancer growth and metastasis by dint of impeding PGK1-mediated Warburg effect." (PMID 38111678, 2023). "The FOXO3A/LINC00926/PGK1 axis effectively inhibits the Warburg effect in breast cancer and is a potential therapeutic target for breast cancer." (PMID 37204526, 2023). "Our cellular assays show that PGK1 is highly expressed in breast cancer and that knockdown of PGK1 expression greatly reduces the activity, invasion, and migration ability of BC cells." (PMID 36860848, 2023). "In breast cancer patients, the FOXO3A/LINC00926/PGK1 axis regulates breast cancer glycolysis, tumour growth, and lung metastasis both in vitro and in vivo." (PMID 37723547, 2023). "In breast cancer patients, miR-16–1-3p inhibits PGK1 expression by directly targeting its 30-untranslated region and represses breast cancer cell proliferation, migration, invasion, and metastasis by inhibiting the PGK1-mediated Warburg effect." (PMID 37723547, 2023). "It suppresses proliferation, migration and invasion of breast cancer cells by inhibiting phosphoglycerate kinase 1 (PGK1) expression via promoting STUB1-driven ubiquitination of PGK1." (PMID 37583933, 2023). "Phosphoglycerate kinase 1 (PGK1), one of the enzymes in the glycolysis process, can promote the progress of breast cancer and have an impact on the prognosis of breast cancer patients." (PMID 38264667, 2023). "The downregulation of PGK1 can obviously inhibit the invasion of breast cancer cells and reverse the EMT process." (PMID 37723547, 2023). "The lncRNA LINC00926 negatively regulates the expression of phosphoglycerate kinase 1 (PGK1) and predicts a favorable clinical outcome for breast cancer." (PMID 38156018, 2023). "The lncRNA LINC00926 promotes STUB1-mediated ubiquitination of PGK1 to downregulate PGK1 expression, thereby suppressing the growth of breast cancer." (PMID 35392171, 2022). "In this axis, LINC00926 inhibits proliferation, migration and invasion in breast cancer via PGK1‐mediated Warburg effect." (PMID 35441740, 2022). "Recently, PGK1 expression was reported as a part of a 7-gene signature and part of a 4-gene signature to predict the survival of breast cancer patients." (PMID 35622738, 2022). "The Hsp90 inhibitor, 17-AAG, rather than HDN-1, disrupted the interaction between Hsp90 and PGK1, and reduced GSK3β expression, resulting in significantly reduced inhibition of β-catenin expression, to maintain the stemness of breast cancer stem cells." (PMID 34403222, 2021). "Other genes were associated with cell adhesion and migration of breast cancer cell [DUOXA1 and PGAM1], prognosis of breast cancer [PGK1 and KLK10], or clinical outcome in breast cancer [RBM3 and AQP5]." (PMID 34497807, 2021). "On the basis of this idea, we examined the effects of PGK1 depletion on genes involved in breast cancer." (PMID 33747900, 2021). "In line with the median value of PGK1 expression, we separated breast cancer subjects into two subgroups." (PMID 34790279, 2021).